OS9 (OS9 endoplasmic reticulum lectin)
Description:
Lectin component of the HRD1 complex, which functions in endoplasmic reticulum (ER) quality control and ER-associated degradation (ERAD). Specifically recognizes and binds improperly folded glycoproteins as well as hyperglycosylated proteins, retain them in the ER, and transfers them to the ubiquitination machinery and promote their degradation. Possible targets include TRPV4 as well as hyperglycosylated HSP90B1.
Synonyms: OS-9; ERLEC2
Tractability: Antibody: UniProt predicts a signal peptide or a membrane-spanning region. PROTAC: ubiquitination databases record sites on it; its protein half-life has been measured.
Gene: Protein-coding gene on chromosome 12 (57,693,841 to 57,728,342, forward strand). Ensembl gene ENSG00000135506.
Subcellular location: Endoplasmic reticulum lumen
Subcellular location (Human Protein Atlas): Endoplasmic reticulum
Pathways (Reactome):
Disease: Defective CFTR causes cystic fibrosis; Hh mutants are degraded by ERAD
Immune System: AMPK-induced ERAD and lysosome mediated degradation of PD-L1(CD274)
Metabolism of proteins: ER Quality Control Compartment (ERQC)
Signal Transduction: Hedgehog ligand biogenesis
Transport of small molecules: ABC-family protein mediated transport
Gene Ontology:
Molecular function: glycosylation-dependent protein binding; protein binding; protease binding
Biological process: ERAD pathway; negative regulation of retrograde protein transport, ER to cytosol; protein retention in ER lumen; protein ubiquitination; response to endoplasmic reticulum stress; ubiquitin-dependent protein catabolic process; retrograde protein transport, ER to cytosol; endoplasmic reticulum unfolded protein response; protein targeting
Cellular component: endoplasmic reticulum; endoplasmic reticulum lumen; Hrd1p ubiquitin ligase complex; endoplasmic reticulum membrane
Genetic constraint (gnomAD): Loss-of-function variants: 52 observed, 73.53 expected, observed/expected ratio (o/e) 0.71, 90% interval 0.56 to 0.89. The upper end of that interval is the gene's LOEUF score, 0.89, which puts it in group 3 of 6, group 1 being the genes least tolerant of losing a copy. Missense variants: 725 observed, 830.65 expected, observed/expected ratio (o/e) 0.87, 90% interval 0.82 to 0.93. Synonymous variants: 269 observed, 325.1 expected, observed/expected ratio (o/e) 0.83, 90% interval 0.75 to 0.92.
Homologues: Orthologues: macaque OS9 (99% identical), chimpanzee OS9 (98% identical), dog OS9 (89% identical), pig OS9 (87% identical), guinea pig OS9 (86% identical), rat Os9 (83% identical), mouse Os9 (81% identical), rabbit OS9 (66% identical), tropical clawed frog os9 (46% identical), zebrafish os9 (43% identical), Caenorhabditis elegans F48E8.4 (20% identical). Paralogues in human: ERLEC1 (16% identical).
Diseases named in the same sentence as OS9 in open-access papers:
OS9 is named in the same sentence as 13 diseases in open-access papers, as found by Europe PMC text mining. Sharing a sentence is not in itself a finding about the gene and the disease. The quoted sentences say what the papers report.
osteosarcoma (4 papers, 2016 to 2021). A usually aggressive malignant bone-forming mesenchymal neoplasm, predominantly affecting adolescents and young adults. "The protein encoded by OS9 is highly expressed in osteosarcoma and binds to hypoxia-inducible factor 1 (HIF-1), a key regulator of hypoxia response and angiogenesis." (PMID 34336645, 2021). "We also found a significant increase in HIF1α (hypoxia-inducible factor 1-alpha) expression with a decrease in the inhibitor of HIF1α, OS9 (Osteosarcoma Amplified 9, Endoplasmic Reticulum Lectin)." (PMID 33917306, 2021). "Protein OS-9 involved in the ubiquitination of misfolded proteins was identified for the first time in a human osteosarcoma cell line, while desmoglein-1 was reported to interact with the testis-specific isoform of Na/K ATPase in the plasma membrane of bovine sperm during capacitation." (PMID 32942548, 2020). "OS-9 is ubiquitously expressed in human tissues and is overly expressed in osteosarcomas." (PMID 27478637, 2016).
rheumatoid arthritis (2 papers, 2018 to 2025). A chronic, systemic autoimmune disorder characterized by inflammation in the synovial membranes and articular surfaces. "As previous studies have implicated Hrd1 in synovial cell proliferation in rheumatoid arthritis, we analyzed the OS9 and Hrd1 protein levels in synovium isolated from patients suffering from either osteoarthritis or rheumatoid arthritis by immunoblotting." (PMID 30167107, 2018). "Moreover, the abundance of OS9 is inversely correlated with Hrd1 level in clinical synovium samples isolated from osteoarthritis and rheumatoid arthritis patients." (PMID 30167107, 2018). "In OA and rheumatoid arthritis (RA) tissues, The expression of OS9 is negatively correlated with HRD1." (PMID 40917753, 2025).
cystic fibrosis (1 paper, 2021). Autosomal recessive disorder caused by pathogenic variants in the CFTR gene (cystic fibrosis transmembrane conductance regulator), which encodes a chloride and bicarbonate channel expressed in epithelial cells, and follow the diagnosis criteria. "In the PPI network of OS9, OS9 and derlin 2 (DERL2) involve in protein processing in the endoplasmic reticulum and complicate CFTR (Cystic fibrosis transmembrane conductance regulator) causes cystic fibrosis pathways, which may be associated with the prognosis of glioma with mutant PTEN." (PMID 34336645, 2021).
glioma (1 paper, 2021). A benign or malignant brain and spinal cord tumor that arises from glial cells (astrocytes, oligodendrocytes, ependymal cells). "The expression of CLCF1, AEBP1, and OS9 is significantly associated with the prognosis of PTEN-wt glioma, indeed which are significantly different between high-risk score patients and low-risk patients in the PTEN-mut subgroup (p < 0.001)." (PMID 34336645, 2021). "Due to the higher malignancy of the PTEN-mut gliomas, we explored the independent prognostic signatures (CLCF1, AEBP1, and OS9) for a potential therapeutic target in PTEN-mut glioma." (PMID 34336645, 2021). "Thus, in the PTEN-mut glioma, CLCF1, AEBP1, and OS9, which are significantly associated with survival time, may induce glioma progression and are critical targets for diagnosis, prognosis prediction, and treatment, giving therapeutic recommendations to glioma with mutant PTEN." (PMID 34336645, 2021). "Due to the higher malignancy of the PTEN-mut glioma, we look for potential therapies targeting the prognostic signatures (CLCF1, AEBP1, and OS9) in this subgroup." (PMID 34336645, 2021). "Therefore, (+)-JQ1 potentially competes for and binds to the CLCF1, AEBP1, and OS9 proteins, resulting in the interruption of the pro-oncogenic pathway in PTNE-mut gliomas." (PMID 34336645, 2021). "CLCF1, AEPB1, and OS9 in the PTEN-mut subgroup are the optimal and independent prognostic signatures and can be used as potential targets for the diagnosis, prediction, and treatment of PTEN-mut glioma." (PMID 34336645, 2021). "Studies on OS9 in glioma have not been reported, but our model demonstrated the strong correlation between OS9 and survival time, indicating that OS9 is also a potential target for glioma." (PMID 34336645, 2021). "To verify that previous identified prognostic genes of TCGA-glioma PTEN-mut are also the prognostic genes in IDH1-wt patients with PTEN-mut, we observed that AEBP1, CLCF1, and OS9 were significantly prognostic genes in IDH1-wt, IDH1-wt/GBM, or IDH-wt/LGG gliomas with PTEN-mut." (PMID 34336645, 2021).
neuroblastoma (1 paper, 2014). Neuroblastoma (NB) is the most common solid, extracranial childhood tumor. "Furthermore, the chromosome 12q arm contains other – in neuroblastoma not infrequently amplified – genes, among them oncogenes and cell cycle-associated genes (MDM2, CDK4, OS9, and GLI1)." (PMID 25161957, 2014).
pancreatic ductal adenocarcinoma (1 paper, 2020). An infiltrating adenocarcinoma that arises from the epithelial cells of the pancreas. "Interestingly, in pancreatic ductal adenocarcinoma (PDAC), another lncRNA ENST00000480739 could inhibit HIF-1α by up-regulating OS9 (osteosarcoma amplified-9) expression through enhancing the acetylation of H3K27 within OS9 gene promoter." (PMID 32370770, 2020).
thymoma (1 paper, 2021). A neoplasm arising from the epithelial cells of the thymus. "Stimulation of the thymoma cell line EL4 with Notch ligand Delta-like 4 (DLL4) induced expression of the genes involved in ERAD including Sel1l, Hrd1, Os9, and Edem1 as well as SEL1L proteins." (PMID 34240701, 2021).
cancer (3 papers, 2018 to 2020). A tumor composed of atypical neoplastic, often pleomorphic cells that invade other tissues. "It has to be stressed that regulation between OS9 and Sel1L in cancer cells needs further investigation." (PMID 29415493, 2018). "It was suggested that ER lectin OS9 (known also as ERLEC2) promotes the tolerance of cancer cells to hypoxia by suppressing transcription of and mediating degradation of HIF 1α factor." (PMID 29415493, 2018). "In a cancer hypoxic condition, MFGE8 might interact with OS9 and therefore releasing HIF1α, resulting in tumor growth and metastasis." (PMID 32591639, 2020).
tumor (2 papers, 2020 to 2021). "Firstly, we selected several genes related to tumor metastasis through the NCBI database and literature, including SRA1, DBF4 zinc finger B (DBF4B), ZNFX1 antisense RNA 1 (ZFAS1), colorectal neoplasia differentially expressed (CRNDE), endoplasmic reticulum lectin (OS9), and others." (PMID 34011971, 2021).
infection (1 paper, 2012). The state of being infected such as from the introduction of a foreign agent such as serum, vaccine, antigenic substance or organism. "We also tested whether OS9 is important for the function of the heavily glycosylated receptor kinase EFR, which is required for the perception of the bacterial EF-Tu during pathogen infection." (PMID 22328055, 2012).
OS9 also shares sentences with these, for which no sentence is quoted: acute kidney injury (1 paper); osteoarthritis (1); squamous cell carcinoma (1).